IL4 (interleukin 4)
Diseases named in the same sentence as IL4 in open-access papers (continued):
Sharing a sentence is not in itself a finding about the gene and the disease.
allergic asthma (continued). "Early studies in murine allergic asthma models have shown that depletion of CD4 + CD25+ Tregs enhances neutrophil and T‐cell recruitment to the airways, IL‐4 and IL‐5 production, and airway hyperreactivity." (PMID 40497455, 2025). "IL-4 and IL-13 via IL4Rα signaling have been known to drive MCM in 10-day-old Tg+ mice and mice models of allergic asthma." (PMID 40406132, 2025). "ILC2s release IL4, IL5, IL9, and IL13, enhancing a type 2 immune response and therefore potentially also promoting the development of allergic asthma." (PMID 40636105, 2025). "The role of IL-4, IL-5, IL-6, IL-33, TNF-α and IFN-γ in the pathogenesis of allergic asthma is well documented has been elaborately explicated elsewhere." (PMID 38807596, 2024). "Research has shown that chronic exposure to Th2 cytokines, such as IL-4 and IL-13, increases CFTR activity, which has been demonstrated in both human airway tissues and mouse models of allergic asthma." (PMID 39664985, 2024). "Eosinophil infiltration and IL-4, IL-5, and IL-13 expression levels were also similar in HDM-induced allergic asthma LysMCreCul5fl/fl mice and Cul5fl/fl mice." (PMID 38177117, 2024). "Circulating CD4+ memory T cells producing both IL-4 and IL-17, as well as IL-23R and CCR6, GATA3, and RORγt, were identified in patients with allergic asthma and with palmoplantar pustulosis." (PMID 38022605, 2023). "It is also possible that the suppressive effect of IL-4 on the functional expression of TRPA1 is a compensation mechanism aiming to limit inflammation and symptoms in allergic asthma." (PMID 37386145, 2023). "Based on this, we investigated the efficacy and mechanism of SXCF in allergic asthma by combining inflammatory factors such as TNF-α, IL-4, IL-10, IFN-γ, serological indicators, behavioural results, and pathological results." (PMID 36937885, 2023). "BM-MSCs preconditioned with EPA decreased BALF inflammatory cell counts, levels of TH2 cytokines (IL-4 and IL-13), lung fibrosis, and the presence of mucus-producing cells, and improved lung function in experimental HDM-induced allergic asthma." (PMID 37007034, 2023). "Interleukin-4 (IL-4) and 12/15 lipoxygenase (12/15-LOX) contribute to mitochondrial dysfunction in allergic asthma and can be reduced by vitamin E supplementation." (PMID 35600628, 2022). "IL-4 was produced by CD4 T cells stimulated by antigen or mitogen, which was closely related to the occurrence of allergic asthma." (PMID 35431951, 2022). "However, the in vivo role of B cell IL-4 per se was unclear, with studies showing that it was required for Th2 responses with resultant worsening of leishmaniasis, but it was not required for Th2 responses and protection from helminthic infections or pulmonary/airway inflammation in allergic asthma." (PMID 35359977, 2022). "The primary mechanism of AIT for allergic asthma is thought the shift from Th2 to Th1 response, accompanied by an increase in IFN-γ levels and a decrease in IL4 levels." (PMID 36032162, 2022). "integerrima reportedly subdued the expressions of inflammatory molecules, TNF-α, IL-4, and IL-5 in the mouse model of ovalbumin (OVA) induced allergic asthma, thereby alleviating pulmonary edema." (PMID 36386162, 2022). "To further reveal the relationship between m6A patterns and allergic asthma, we investigated the correlation between m6A patterns and thymic stromal lymphopoietin (TSLP), interleukin (IL)-33, IL-4, IL-5, and IL-13." (PMID 33763115, 2021). "Morin treatment downregulated the expression of BLT2, NF-κB, and Th2-cytokine (IL-1β, IL-4, IL-6, IL-13, and TNF-α) in the lungs of an allergic asthma rat model." (PMID 33917985, 2021). "Macrophage accumulation in the lung is characteristic of murine models of allergic asthma and the cells often bear the hallmarks of AAM/M(IL4)s (e.g. arginase-1+, FIZZ1+, Ym1+)." (PMID 34691050, 2021).
allergic asthma (continued). "We therefore provide evidence for the indispensable role of IL-4Rα signaling in maintaining Treg stability and IL-4–responsive Tregs in limiting IL-33–derived ILC2-driven AHR and airway inflammation in HDM-induced allergic asthma." (PMID 32931477, 2020). "In murine allergic asthma, CHI3L3 is highly expressed, correlated to levels of IL-4 and IL-13, binds to carbohydrates e.g. heparin/heparan sulfate proteoglycan; which are major contributors of pulmonary fibrosis (by stimulating TGF-β signaling in fibroblasts)." (PMID 32024540, 2020). "Oral administration of L. plantarum KTCT3104, L. curvatus KTCT3767, and Lactobacillus reuteri ATCC23272 was shown to alleviate allergic asthma by inhibiting AHR and reducing the production of Th2 cytokines, such as IL-4 and IL-5 in BAL fluids." (PMID 31231389, 2019). "Immune-mediated inflammation is the principal factor involved in allergic asthma pathogenesis, and a variety of inflammatory mediators and cytokines are involved in this process, including interferon-γ (IFN-γ), interleukin-4 (IL-4) and immunoglobulin E (IgE)." (PMID 31545493, 2019). "In addition, SG treatment could alleviate allergic asthma by reducing the inflammatory cells in bronchoalveolar lavage (BAL) fluid and by decreasing inflammatory factors, including IL-4, IL-5, IL-13, eotaxin, and IgE, which are linked with the decreased expression of iNOS and COX-2." (PMID 31572487, 2019). "Overall, these findings indicate that iNKT cells promote allergic asthma inflammation and AHR principally through the secretion of IL-4 and IL-13." (PMID 30105031, 2018). "The pathophysiological features of allergic asthma, including airway remodeling, are thought to result from the expansion of CD4+ T cells producing predominantly Th2 cytokines, interleukin-4 (IL-4), IL-5, and IL-13." (PMID 30374355, 2018). "The increase in TIGIT expression and its attenuation by DW2008S in mice with allergic asthma appear to be limited to FOXP3− effector T cells, which seems to mostly result from fluctuations in number of TIGIT+ IL‐4+ Th2 cells." (PMID 29512870, 2018). "Allergic asthma is an inflammatory airway disorder mediated by TH2 cells, which produce various effector cytokines (IL-4, IL-5, and IL-13)." (PMID 29696026, 2018). "In our present work, we demonstrate that IL-9, which is mainly produced by Th9 cells in children with allergic asthma, impairs IFN-γ production and synergistically promotes IL-4-induced IgE secretion." (PMID 28724400, 2017). "We first detected the production of IL-9 and IL-4, and IFN-γ by PBMCs from children with allergic asthma compared with healthy children of similar age." (PMID 28724400, 2017). "Results showed that compared with healthy children, levels of IL-9, IL-4 and PU.1 were elevated and levels of IFN-γ were lower in children with allergic asthma." (PMID 28724400, 2017). "We confirmed IL-4 exposure induces CCL26 production in A549 cells, thereby modelling an aspect of airway inflammation of relevance to allergic asthma." (PMID 27845745, 2016). "For example, in allergic asthma, OPN enhances sensitization but downmodulates Th2-driven IL-4-dominated inflammation." (PMID 27199509, 2016). "We also evaluated serum IgE production and Th2 inflammatory molecules generated by CKA-induced allergic asthma to ensure that MMDT inhibited the secretion of IgE and BALF inflammatory cytokines IL-4, IL-5, and IL-13." (PMID 24723965, 2014). "We also evaluated serum IgE production and Th2 inflammatory molecules generated by OVA-induced allergic asthma to ensure that EA decreased the levels of IgE and BAL fluid inflammatory cytokines, IL-4, IL-5, and IL-13." (PMID 22649477, 2012). "In the present study, ST36 EA stimulation suppressed the increased antigen-specific IgE production and Th2 cytokines such as IL-4, IL-5, and IL-13 in OVA-induced allergic asthma mice." (PMID 22649477, 2012).
allergic asthma (continued). "Wnt10b deficiency mice of allergic asthma results in enhanced memory T cell activation, increased Th2 polarization as evidenced by elevated IL-4 and IL-13 concentrations, and recombinant Wnt10b increases the percentage of naïve CD4+T and CD8+T cells in vitro, thereby mitigating allergic asthma." (PMID 40433386, 2025). "It is important to acknowledge that the levels of IgE and the Th2 cytokines IL4 and IL13 were also elevated in RSV-infected females, suggesting that these mice could be more vulnerable to allergic asthma." (PMID 40143355, 2025). "Thus, we treated BMDMs with various allergic asthma-related cytokines, including TSLP, IL-33, IL-13, and IL-4." (PMID 38177117, 2024). "While IL-4 is described to be more important in allergic asthma cases, it also plays a significant role in non-allergic phenotypes." (PMID 39001236, 2024). "In experimental ovalbumin-induced allergic asthma, activation of BM-MSC TLR2 by the agonist Pam3CSK4 led to a reduction in levels of BALF TH2 cytokines (IL-4 and IL-5) and eosinophil counts in lungs, resulting in attenuation of airway resistance in response to incremental doses of methacholine." (PMID 37007034, 2023). "Other cells involved in allergic asthma include mast cells that also undergo degranulation to release mediators such as tryptase, histamines, tumour necrosis factor (TNF)-α and various cytokines (e.g. interleukin (IL)-4, IL-5, IL-6 and stem cell factor (SCF))." (PMID 36911735, 2023). "Serum was more effective than BALF in preconditioning BM-MSCs and led to a significant reduction in lung inflammatory cell counts and levels of TH2 cytokines (IL-4 and IL-13) and eotaxin, and lung function improved in a murine model of HDM-induced allergic asthma." (PMID 37007034, 2023). "In addition, BATF, together with IRF4 and STAT, binds to Il-4 CNS2 to trigger IL-4 expression and boost Tfh cell differentiation, which prevents allergic asthma and peripheral lymphomas." (PMID 35812386, 2022). "At present, there is consensus that M2a cell is elicited by IL-4- and IL-13 and secret high levels of IL-13 and chemokines, including TARC and CCL24, that activate Th2 immunity and promotes eosinophil trafficking, which induces allergic asthma." (PMID 36175886, 2022). "We extracted total RNA from the lung tissue of mice from both the control and the F2-administered groups in the allergic asthma model and examined the changes in the Th2 cytokines IL-4, IL-5, and IL-13, eosinophil-recruiting chemokine CCL11 and allergic asthma-related cytokine IL-33 using RT-qPCR." (PMID 34576124, 2021). "Different effects of quercetin such as, inhibitory effect on mast cell activation, eosinophil activation, relaxation of tracheal ring, reduction in IL-4 and IgE serum, blocking airway epithelial cell IL-8 and MCP-1 expression suggest a valuable role of quercetin for allergic asthma." (PMID 32467711, 2020). "We confirmed that the OVA-induced allergic asthma is mainly driven by the Th2 response, following the production of IL-5 and IL-13, but not IL-4, and that PGT treatment greatly reduced such induction." (PMID 33374657, 2020). "In terms of the recurrence number of the allergic asthma participants and the ACT score, allergic asthma also improved at 18 and 30 weeks of the trial, which may be related to the changes of the levels of IgE, Th1 and Th2 cells, IFN-γ, and IL-4 cytokine." (PMID 32509851, 2020). "Therefore, in order to study the immunoregulatory mechanism of RHAS in the treatment of allergic asthma, we measured the serum levels of IgE, IFN-γ, and IL-4 by ELISA." (PMID 32509851, 2020). "A previous study indicated that FMT 10 mg/kg administrated by intraperitoneal injection could significantly alleviate AHR and decrease Th2 cytokines (IL-4, IL-5, and IL-13) levels in the HDM-induced inflammation of allergic asthma." (PMID 33013383, 2020).
allergic asthma (continued). "Recent studies show that IL-4 upregulates the Cl-/SCN- exchange activity of pendrin and increases OSCN- production, which results in NF-κB activation and induces airway inflammation in a murine allergic asthma model 22,26." (PMID 32929324, 2020). "Elevated levels of IL-4 and IL-5 are present in BAL of patients with allergic asthma." (PMID 31772507, 2019). "To evaluate the effects of pitavastatin as a treatment for allergic asthma on IFN-γ and IL-4 mRNA and protein expression, we assessed IFN-γ and IL-4 mRNA expression levels in BALF using RT-PCR and IFN-γ and IL-4 protein expression levels in the lungs through western blot analysis." (PMID 28729731, 2017). "Immunological hallmarks of allergic asthma include eosinophilia in patient bronchoalveolar lavage (BAL) fluid, sputum or bronchial biopsies, Th2 polarised CD4+ T cells secreting type 2 cytokines (including IL-4, IL-5 and IL-13), and IgE antibody." (PMID 27256370, 2016). "Besides relieving AHR, which we have already known clinically, we demonstrated its efficacy in reducing IL-4 and IgE levels in BALF in murine model of allergic asthma." (PMID 26035827, 2015). "We hypothesized that airway allergen challenge would induce an elevated expression profile of two critical Th2 cytokines, IL-4 and IL-13, in the HDM sheep model of allergic asthma." (PMID 26362930, 2015). "IL-4 and IL-13 are two central Th2 effector cytokines upregulated in OVA-induced allergic asthma." (PMID 25058417, 2014). "For instance, expression of the IL-4 receptor alpha, which is required for both IL-4 and IL-13 signalling is not required on smooth muscle cells for the development of experimental allergic asthma." (PMID 21677778, 2011). "The unbalance of Th1/Th2 cells response in allergic asthma shows that the IL-4, IL-5, and IL-13 and its respective transcription factor STAT6 remains intensely upregulated at the expense of a drastic decrease of T-bet levels in the airway of individuals with allergic asthma." (PMID 36685604, 2022). "The source of IL‐4 cytokine targeted by Hp‐TGM in our models remain unknown, however, T follicular helper cells (Tfh) may well be the primary target of Hp‐TGM since they are the main producer of IL‐4 in allergic asthma." (PMID 35758054, 2022). "ILC2 mainly produced IL-5 and IL-13, but not IL-4, in an allergic asthma model." (PMID 32915886, 2020). "Likewise, the absence of Mrp4 did not affect the release of the cytokines IL-4 and IL-5, which both play an essential role during allergic asthma." (PMID 23613808, 2013). "Interestingly, the midpregnancy cytokine profile we describe in the ASD group in the present study (increased IL-4, IL-5 and IFN-γ) may be consistent with an allergic asthma clinical phenotype." (PMID 21810230, 2011). "IL‐4 were not affected by different doses of recombinant protein injected before and after OVA induced allergic asthma." (PMID 38888451, 2024). "Nonetheless, since Th2 cells are not the only source of Th2 cytokines in the lungs in allergic asthma, AHR and lung secretion of IL-4 and IL-5 induced by OVA was increased in both A/J and BALB/c." (PMID 34924814, 2021). "In an allergic asthma model, BPE-induced airway inflammation was demonstrated to be dependent on TLR4, influencing immune cell infiltration and the local production of IL-4 and IL-10 cytokines, without affecting airway hyperresponsiveness (AHR)." (PMID 35386993, 2021). "Meanwhile, the release of IgE and IL-4 reduced (P < 0.05), and the release of IFN-γ did not significantly change in the allergic asthma group." (PMID 32509851, 2020). "IL-4 is critical in class switching of B cells to generate IgE40; however, whether signaling through the IL-4Rα on B cells is required for the generation of TFH cells and IgE has not been investigated in the context of allergic asthma." (PMID 33383090, 2021).
allergic asthma (continued). "In addition, IL-9-expressing CD4+ T cells did not co-express IL-4, indicating that large percentage of IL-9-expressing CD4+ T cells in children with allergic asthma might be Th9 cells in origin, instead of Th2 cells." (PMID 28724400, 2017).
helminth infection (252 papers, 2006 to 2026). "ILC2s have been implicated in immune responses to extracellular helminth infections via the secretion of the type 2 cytokines IL-4, IL-5, IL-9 and IL-13." (PMID 40591723, 2025). "Taken together, our results demonstrate downregulation of MINCLE expression on monocytes and macrophages by IL-4 as a possible mechanism of thwarted Th17 vaccination responses by underlying helminth infection." (PMID 36753434, 2023). "IL-4 is a hallmark cytokine in helminth infections, which appear to increase the risk for mycobacterial infection and active tuberculosis." (PMID 36753434, 2023). "The local cytokine environment during acute helminth infection alters latent herpesvirus infection, whereby IL-4 reactivated human Kaposi’s sarcoma-associated herpesvirus from latency in cultured human cells." (PMID 39816832, 2023). "Helminth infections, including Ascaris, have been linked to Th2 polarized immune responses with prominent IL-4 and IL-5 expression that typically contrasts with the Th1 immune responses associated with viral and bacterial infections." (PMID 37622109, 2023). "Helminth infections are associated with a Th2 dominant immune response with increased production of IL-4, IL-5, and IL-13." (PMID 35976976, 2022). "The immunological hallmark of helminth infections is their ability to induce Th-2 associated immune responses characterized by the presence of the IL-4, IL-5, IL-9, IL-10, and IL-13." (PMID 35087402, 2021). "AAMs are one of the most important sources of IL-4 and IL-13 during helminth infection, and liver fibrosis is associated with AAMs infiltration." (PMID 34733286, 2021). "In helminth infections, TCRγδ+ cells are associated, through the secretion of IL-4, IL-5 and IL-13, with the development of a Th2 response." (PMID 33023672, 2020). "While eosinophils release IL-4 and aid in type 2 T cell polarization, eosinophil deficient mice still mount a normal T helper type 2 (Th2) response to helminth infection." (PMID 33193446, 2020). "Previously, it was noted that a type-2 immune response was responsible to helminth infections, which were usually associated with IL-10, IL-5 and IL-4 secretions." (PMID 32228657, 2020). "The previous research of defense mechanisms against helminths infections is typically associated with a type 2 immune response characterized by the expression of the cytokines IL-3, IL-4, IL-5, IL-9, IL- 10, and IL-13." (PMID 32243446, 2020). "Some previous studies have shown that Th2 immune responses associated with helminths infection were characterized by the induction of IL-4, IL-13, IgG, IgG1, and IgE antibodies in rats, and the generation of IL-3, IL-4, IL-5, and IL-13 in mice." (PMID 32971770, 2020). "Helminths infection elicited strong Th2 cell responses associated with significant productions of interleukin (IL)-4, IL-5, IL-9, IL-10, IL-13, IL-25, and IL-31." (PMID 32971770, 2020). "Helminth infection is associated with a Th2 immune response marked by the production of interleukin-4 (IL-4), IL-5 and IL-13 enhancing IgG4 and IgE antibody responses and the expansion of effector cells, including eosinophils, mast cells and basophils." (PMID 33604551, 2019). "IHIs is associated with the production of interleukin 4 (IL-4), IL -5, IL-9, IL-10, and IL-13 in the host and is likely to play a vital role in decreasing the severity of acute diseases caused by helminth infection." (PMID 31613921, 2019). "Helminth infection in the intestine was associated with a significant upregulation of IL-4 and IL-13 expression in lung tissue." (PMID 31673002, 2019). "We stimulated human monocyte-derived macrophages with zinc sulfate, in combination with 3 different concentrations of IL-4 or IL-13 (cytokines associated with a Th2 response to helminth infection)." (PMID 31841569, 2019). "Helminth infections are typically associated with Type 2 cytokine responses with elevated levels of IL-4, IL-5 and IL-13." (PMID 30897083, 2019).